BRD7 (bromodomain containing 7)
Diseases named in the same sentence as BRD7 in open-access papers (continued):
Sharing a sentence is not in itself a finding about the gene and the disease.
tumor (continued). "BRD7 functions as a crucial tumor suppressor in numerous malignancies." (PMID 34109174, 2021). "We also find that the STK11, CD14, and BRD7 genes in the manatee were also well conserved, suggesting that extant manatees may also have enhanced tumor suppression and an augmented stress response." (PMID 33513090, 2021). "The results showed that BRD7 overexpression significantly inhibited tumor growth and that the tumor weight was lower in the BRD7 overexpression group than in the control group, but the tumor weight was recovered after YB1 restoration." (PMID 32028981, 2020). "Notably, IHC of primary tumor samples was used to detect the alterations of BRD7, YB1, Ki67, E-cadherin and vimentin." (PMID 32028981, 2020). "Here, we summarize the role of BRD7 as a tumor suppressor in various organs." (PMID 32992509, 2020). "BRD7 inactivation makes tumour cells become targetable for T-cell-mediated killing." (PMID 35746919, 2020). "Furthermore, a series of rescue experiments confirmed that BRD7 blocks tumor growth, EMT and metastasis through a YB1-mediated malignant phenotype." (PMID 32028981, 2020). "It is pointed out in the literature that BRD7-deficient tumor cells exhibit increased sensitivity to interferon- γ, promote the activation of effector T cells and kill tumor cells, suggesting that BRD7 may be a very promising target for tumor immunotherapy." (PMID 32028981, 2020). "We have described previously that BRD7 has potent anti-proliferative and tumor suppressor activity at least partially through transcriptionally repressing miR-141, which directly targets the 3’UTR of PTEN mRNA and subsequently contributes to AKT pathway activation in NPC." (PMID 29559001, 2018). "Thus, interference in BRD7 expression offers therapeutic potential for inhibition of angiogenesis and tumor growth via multiple mechanisms." (PMID 28951988, 2017). "Therapeutic induction of BRD7 expression might not only be valuable in reducing tumor cell proliferation, but also in reducing tumor angiogenesis and increasing anti-tumor immune infiltration." (PMID 28951988, 2017). "Thus, in addition to its tumor suppressive properties, the expression profile of BRD7 is also suggestive of angiosuppressor functions." (PMID 28951988, 2017). "BRD7 is a tumour suppressor and induces apoptosis in multiple cancers." (PMID 27957794, 2017). "In this study, we investigated the role of BRD7 in tumor angiogenesis." (PMID 28951988, 2017). "Decreased BRD7 expression was found to be significantly associated with TNM stage and tumor size." (PMID 26919247, 2016). "Notably, IHC staining of tumor sections of xenografts demonstrated that the overexpression of BRD7 significantly induced the expression of PTEN and decreased the phosphorylation of p-AKT in the 5-8F/BRD7 tumors compared with the 5-8F/mock tumors." (PMID 27010857, 2016). "In addition, the expression of BRD7 and miR-141 in xenograft tumor tissues was confirmed by western blot and by qRT-PCR assays, respectively." (PMID 27010857, 2016). "In conclusions, our data indicated that BRD7 may serve as a tumor suppressor in HCC and may be a novel molecular target for the treatment of HCC." (PMID 26919247, 2016). "BRD7 was down-regulated in tumor tissues and HCC cell lines." (PMID 26919247, 2016). "BRD7, as a tumor suppressor, could inhibit cell-cycle progression and initiate apoptosis; meanwhile, BRD7 could downregulate oncomiR-141 expression." (PMID 27010857, 2016). "More recent studies also suggest that BRD7 functions as a tumor suppressor gene." (PMID 26919247, 2016).
tumor (continued). "Subsequently, we selected tumour tissues from three representative nude mice of each group, and the Western blot results demonstrated that, in comparison to the control group, the expression of BRD7 was elevated in both the stable expression of dCas9‐TET1CD‐sgRNA2 and dCas9‐TET1CD‐sgRNA5 groups." (PMID 41510594, 2026). "However, the molecular mechanism of the downregulation of BRD7 expression and whether the strategy of activating BRD7 expression plays anti‐tumour effects still needs to be clarified." (PMID 41510594, 2026). "Taken together, our findings proved that BRD7 functions as a tumor suppressor at least partially by inhibiting enhancer activity and the expression of BIRC2 in NPC, and targeting the BRD7/BIRC2 axis might provide a potential strategy for the diagnosis and treatment of NPC." (PMID 36788209, 2023). "However, the mechanism underlying the tumor-suppressive effect of BRD7 as a transcription factor in NPC has not yet been clearly explored." (PMID 36788209, 2023). "Therefore, there are multiple reports that challenge the role of BRD7 as a tumor suppressor." (PMID 35323214, 2022). "BRD7, as a potential tumor suppressor, may suppress HCC tumorigenicity." (PMID 33531996, 2021). "Therefore, based on our research, the development of anti-tumor small molecule inhibitors targeting BRD7/c-Myc axis could be an attractive approach in solving the problem of c-Myc “undruggable” and the clinical targeted therapy of CRC." (PMID 34109174, 2021). "BRD7 was also shown to have an anti-inflammatory role during early acute inflammation via interference with activation of the NF-кB signaling pathway, which indicated that BRD7 may affect tumor development through regulation of the inflammatory components in the tumor microenvironment." (PMID 33531996, 2021). "However, the precise molecular mechanism underlying the tumor suppressive effect of BRD7 in HCC progression, specifically, has not yet been clearly elucidated." (PMID 33531996, 2021). "Therefore, we sought to determine whether YB1 plays an essential role in the BRD7-mediated tumor suppressor function." (PMID 32028981, 2020). "While in tumor cells loss of chromosome 16q12 may be responsible for reduced expression of BRD7, loss of heterozygosity is not a common phenomenon in TEC which are considered non-transformed cells." (PMID 28951988, 2017). "Indeed, the tumor suppressor characteristics of BRD7 are well known." (PMID 26919247, 2016). "Moreover, our study found that BRD7 overexpression suppressed the migration and invasion of Bel7402 and Hep3B cells in vitro, which suggests that BRD7 may play a role in tumor metastasis." (PMID 26919247, 2016). "Furthermore, the activation of the PTEN/AKT pathway mediated by the overexpression of BRD7 could be inhibited by rescuing the expression of miR-141, which accordingly results in the partial restoration of cell proliferation and tumor growth." (PMID 27010857, 2016). "Therefore, we hypothesized that miR-141 might be involved in BRD7-mediated cell proliferation and tumor formation in the progression of NPC." (PMID 27010857, 2016). "Accumulating evidence indicates that BRD7 may serve as a tumor suppressor." (PMID 24840027, 2014). "BRD7 was confirmed to be down‐expressed in NPC and acts as a tumour suppressor in NPC by negatively regulating signalling pathways like ERK, Rb/E2F and PI3K/AKT, thereby inhibiting tumour progression and metastasis." (PMID 41510594, 2026). "Our preliminary research has confirmed that BRD7 is down‐regulated in NPC and functions as a tumour suppressor gene." (PMID 41510594, 2026).
tumor (continued). "To assess the impact of BRD7 on anti-tumor immunity in NPC, we examined the infiltration of CD8+ T lymphocytes in tumor tissues." (PMID 40083706, 2025). "Western blot analysis detected the expression of BRD7, PD-L1, and molecules related to the PI3K/AKT signaling pathway in tumor tissues." (PMID 40083706, 2025). "The recovery of BRD7 expression reversed the inhibitory effects of TRIM25 knockdown on the proliferation, tumor growth, and paclitaxel resistance of BC cells in vitro and in vivo." (PMID 41315221, 2025). "As shown, BRD7 promoted the infiltration of CD8+ T lymphocytes, thereby enhancing their cytotoxicity against tumor cells." (PMID 40083706, 2025). "Our previous study demonstrated that BRD7 is downregulated in NPC and exerts a tumor-suppressive effect by inhibiting the malignant progression and metastasis of NPC." (PMID 39664566, 2024). "We have previously demonstrated that BRD7 is expressed at low levels in both NPC tissues and cells, and it has been proven to be an important tumor suppressor in NPC9." (PMID 39664566, 2024). "Our previous studies demonstrated that BRD7 is expressed at low levels in NPC and functions as a tumor suppressor to inhibit NPC progression and metastasis." (PMID 39664566, 2024). "TP-472, which has less selectivity for BRD9 over BRD7 compared to other BRD9 inhibitors, blocked melanoma tumorigenicity and tumor growth in vivo as well as suppressed the proliferation of uterine leiomyosarcoma cells." (PMID 38390898, 2024). "BRD7 is a subunit of PBAF in the mSWI/SNF complex family and has served as a tumor suppressor protein during tumorigenesis in recent years." (PMID 36728436, 2023). "The results showed that BRD7 was successfully overexpressed in xenograft tumor tissues and that the expression of BIRC2 was decreased in the BRD7 overexpression group." (PMID 36788209, 2023). "Biologically, the BRD7-USP1-CHK1 axis regulates the sensitivity of tumor cells to chemotherapeutic drugs targeting CHK1, suggesting BRD7 as a new potential molecular target for effective anti-cancer therapy." (PMID 37626049, 2023). "Meanwhile, the expression of BRD7 and BIRC2 in xenograft tumor tissues was confirmed by Western blotting." (PMID 36788209, 2023). "BRD7 is involved in NPC tumor development and progression as a tumor suppressor and negatively regulates the expression of BIRC2." (PMID 36788209, 2023). "Bromodomain-containing protein 7 (BRD7), known as celtix-1, is a tumor suppressor that participates in transcriptional regulation by interacting with acetylated histones on chromosomes." (PMID 38105650, 2023). "Not only circRNAs, but also some protein-coding genes and other non-coding RNAs, such as bromodomain containing 7(BRD7), YY1, and miR-141, play dual functions in tumor development and progression." (PMID 36231036, 2022). "Since the initial discovery that levels of BRD7 are decreased in NPC, BRD7’s role as a tumor suppressor has been underscored in the HNE2 NPC cell line, in which BRD7 inhibits cell growth and G1-S cell cycle progression." (PMID 32992509, 2020). "Decreased BRD7 expression was correlated with clinical parameters including TNM stage, tumor size, shorter OS and RFS, and was an unfavorable prognostic marker for HCC." (PMID 32927435, 2020). "Given that BRD7 is required for XAF1 transcription, BRD7 likely serves a tumor-suppressive role in NSCLC." (PMID 32992509, 2020). "Our previous results confirmed that BRD7 negatively regulates the AKT signaling pathway to inhibit cell proliferation and tumor formation." (PMID 32028981, 2020). "We identified nineteen putative angiosuppressor genes, one of them being bromodomain containing 7 (BRD7), a gene that has been assigned tumor suppressor properties." (PMID 28951988, 2017). "Tumor growth was significantly suppressed by INF-γ treatment, but BRD7 depletion prevented the decrease in tumor growth by INF-γ treatment." (PMID 26802028, 2016).
tumor (continued). "Taken together, our results suggested that BRD7 serve as a potential tumor suppressor and as a new molecular target for the treatment of HCC, although the precise molecular mechanism by which BRD7 regulates HCC progression remains to be elucidated." (PMID 26919247, 2016). "Cellular gene alterations also contribute to NPC development, especially inactivation of tumor suppressor genes, such as SPLUNC1, UBAP1, BRD7, NOR1, NGX6 and LTF, which are involved in different stages of NPC initiation and progression." (PMID 19949542, 2009). "Similarly, the interaction between BRD7 and MYC underscores the balance between tumor suppression and oncogenesis." (PMID 41404623, 2025). "Meanwhile, compared with the siNC plus PTX group, TRIM25 knockdown significantly increased the anti-tumor effect of PTX, and restoring BRD7 expression could significantly reverse the effect of TRIM25 knockdown on paclitaxel chemotherapy." (PMID 41315221, 2025). "Although our study suggested that BRD7 could serve as an effective target to inhibit the growth of NPC and promote anti-tumor immunity in vivo, this study still has certain limitations." (PMID 40083706, 2025). "Silencing of BRD7 significantly increased the protein levels of CHK1 but not of CHK2, and this effect was consistently observed in multiple tumor cell lines, including U2OS, H1792, H358, HCT116, SKBR3, and MCF7, suggesting that BRD7 negatively regulates the expression of CHK1 protein." (PMID 37626049, 2023). "Our data demonstrate that dcPBAF does not contain Brd7 which is an important subunit of PBAF known as a tumor suppressor that inhibits growth and metastasis and initiates apoptosis in cancer cells." (PMID 38033872, 2023). "Indeed, the tumor cells were significantly sensitized to the three CHK1 inhibitors, AZD7762, PF477736, and LY2603618, upon BRD7 silencing and CHK1 accumulation (lanes 5 versus 1), in a dose-dependent manner." (PMID 37626049, 2023). "More surprisingly, 70% of BRD7+/+ mice displayed tumor nodules in the colorectum, while no tumor nodules were observed in the BRD7–/– group." (PMID 34109174, 2021). "Interestingly, the same group of researchers found that bromodomain-containing protein 7 (BRD7), a tumor suppressor gene, is a component of UPR signaling and can regulate the nuclear translocation of XBP1." (PMID 33558590, 2021). "BRD7/9 belong to the BRD-containing family of epigenetic regulators, which function as readers and regulate gene transcription, DNA replication, and cell-cycle progression, thus playing an important role in tumor growth and development." (PMID 34771678, 2021). "Considering the general role of BRD7 as a tumor suppressor, its regulation of the G1-S transition in NPC cells, and involvement in nutrient-sensing pathways, it is possible that BRD7 participates in the late G1 metabolic checkpoints mediated by essential amino acids, glutamine, and mTOR." (PMID 32992509, 2020). "We previously confirmed that BRD7 plays an inhibitory effect on cell cycle progression by inhibiting the nuclear translocation of β-catenin and the activation of the ERK1/2 pathway in NPC, thus blocking tumor growth." (PMID 32028981, 2020). "Therefore, the present study provides corroborating evidence that BRD7 inhibits cell proliferation, EMT and metastasis through YB1-mediated induction of tumor growth and metastasis." (PMID 32028981, 2020). "Our findings demonstrated that BRD7 expression and c-Myc activation forms a negative feedback loop to control the cell proliferation and tumor growth by targeting miR-141." (PMID 29559001, 2018). "We show that suppression of BRD7 induces a pro-angiogenic cytokine and gene expression profile, whereas increased expression of BRD7 induces NFκB-mediated ICAM1 expression which promotes anti-tumor immunity." (PMID 28951988, 2017).
tumor (continued). "Interestingly, the previously reported tumor angiogenesis gene HMGB1 displays parallel actions to BRD7 knockdown as it induces the expression of different pro-angiogenic cytokines, including IL8, CXCL1 and CXCL6." (PMID 28951988, 2017). "BRD7, a subunit of the PBAF-specific SWI/SNF chromatin-remodeling complex, plays a key role as a transcriptional cofactor in the regulation of several important tumor suppressors and tumor-related signaling pathways." (PMID 26919247, 2016). "Real-time quantitative PCR of the 34 paired HCC tissue samples revealed significantly lower BRD7 mRNA expression in tumor tissues compared with adjacent non-tumor tissues (P = 0.019)." (PMID 26919247, 2016). "In this study, we presented the first evidence that BRD7 expression was significantly down-regulated at both the mRNA and protein level in most primary HCC tumor tissues and in HCC cell lines compared with corresponding noncancerous tissues and normal liver cells." (PMID 26919247, 2016). "A series of in vitro experiments demonstrated that the demethylation systems guided by sgRNA2 and sgRNA5 could promote transcriptional activation and BRD7 expression by reducing its methylation, inhibiting the proliferation, migration, invasion of NPC cells and tumour growth in vivo." (PMID 41510594, 2026). "It was confirmed that dCas9‐TET1CD‐sgRNA2&5 could inhibit tumour growth in vivo by targeting BRD7 for transcriptional activation, demonstrating good anti‐tumour effects without exhibiting in vivo toxic side effects." (PMID 41510594, 2026). "To investigate whether BRD7 can inhibit NPC growth and immune escape in vivo, we established a xenograft tumor model in nude mice for in vivo experiments and applied adoptive T cell therapy to tumor-bearing mice." (PMID 40083706, 2025). "To ascertain that suppression of BIRC2 expression by BRD7 is responsible for BRD7’s tumor suppressor function in NPC tumorigenesis and tumor progression, we sought to determine whether the restoration of BIRC2 expression reverses the tumor-suppressive roles of BRD7 induced in vivo." (PMID 36788209, 2023). "Interestingly, BRD7 has recently been reported to regulate protein stability via ubiquitin-dependent proteasome pathway to inhibit cell growth, suggesting its non-transcriptional functions in tumor cells." (PMID 37626049, 2023). "H&E staining demonstrated that tumor necrosis induced by IFN-γ treatment was decreased in the BRD7-depleted group and that IFN-γ-induced XAF1 expression was not shown in BRD7-depleted tumors." (PMID 26802028, 2016).